H2AC7 (H2A clustered histone 7)
Description:
Core component of nucleosome. Nucleosomes wrap and compact DNA into chromatin, limiting DNA accessibility to the cellular machineries which require DNA as a template. Histones thereby play a central role in transcription regulation, DNA repair, DNA replication and chromosomal stability. DNA accessibility is regulated via a complex set of post-translational modifications of histones, also called histone code, and nucleosome remodeling.
Synonyms: H2AFG; HIST1H2AD; H2A/g; H2A.3
Tractability: PROTAC: UniProt records ubiquitination sites on it; ubiquitination databases record sites on it.
Gene: Protein-coding gene on chromosome 6 (26,198,784 to 26,199,293, reverse strand). Ensembl gene ENSG00000196866.
Subcellular location: Nucleus; Chromosome
Subcellular location (Human Protein Atlas): Nucleoplasm
Pathways (Reactome):
Gene expression (Transcription): B-WICH complex positively regulates rRNA expression; DNA methylation; ERCC6 (CSB) and EHMT2 (G9a) positively regulate rRNA expression; MLL4 and MLL3 complexes regulate expression of PPARG target genes in adipogenesis and hepatic steatosis; NoRC negatively regulates rRNA expression; PRC2 methylates histones and DNA; RNA Polymerase I Promoter Escape; RNA Polymerase I Promoter Opening; RUNX1 regulates genes involved in megakaryocyte differentiation and platelet function; RUNX1 regulates transcription of genes involved in differentiation of HSCs; Regulation of endogenous retroelements by KRAB-ZFP proteins; Regulation of endogenous retroelements by Piwi-interacting RNAs (piRNAs); Regulation of endogenous retroelements by the Human Silencing Hub (HUSH) complex; SIRT1 negatively regulates rRNA expression; Transcriptional regulation by small RNAs
Chromatin organization: CHD1 and CHD2 subfamily; CHD6, CHD7, CHD8, CHD9 subfamily; ChAHP complex assembly; HATs acetylate histones; HDACs deacetylate histones; Interaction of NuRD complexes with transcription factors; NuRD complex assembly; RMTs methylate histone arginines
Cell Cycle: Condensation of Prophase Chromosomes; Deposition of new CENPA-containing nucleosomes at the centromere; Inhibition of DNA recombination at telomere; Packaging Of Telomere Ends
DNA Repair: Cleavage of the damaged purine; Cleavage of the damaged pyrimidine; Recognition and association of DNA glycosylase with site containing an affected purine; Recognition and association of DNA glycosylase with site containing an affected pyrimidine
Disease: Defective pyroptosis; Dengue Virus-Host Interactions; HCMV Early Events; HCMV Late Events
Metabolism of proteins: Amyloid fiber formation; Metalloprotease DUBs; UCH proteinases; Ub-specific processing proteases
Signal Transduction: Activated PKN1 stimulates transcription of AR (androgen receptor) regulated genes KLK2 and KLK3
and 15 more pathways
Gene Ontology:
Molecular function: structural constituent of chromatin; DNA binding; protein heterodimerization activity
Biological process: heterochromatin formation
Cellular component: extracellular exosome; nucleoplasm; nucleus; nucleosome; chromosome
Genetic constraint (gnomAD): Loss-of-function variants: 15 observed, 8.47 expected, observed/expected ratio (o/e) 1.77, 90% interval 1.11 to 1.96. That is too few expected variants to judge how well the gene tolerates losing a copy. Missense variants: 283 observed, 187.11 expected, observed/expected ratio (o/e) 1.51, 90% interval 1.37 to 1.67. Synonymous variants: 168 observed, 85.93 expected, observed/expected ratio (o/e) 1.96, 90% interval 1.69 to 1.99.
Homologues: Orthologues: chimpanzee H2AC7 (100% identical), rabbit H2AC7 (99% identical), dog H2AC15 (98% identical), Drosophila melanogaster His2A:CG31618 (85% identical), Drosophila melanogaster His2A:CG33808 (85% identical), Drosophila melanogaster His2A:CG33814 (85% identical), Drosophila melanogaster His2A:CG33817 (85% identical), Drosophila melanogaster His2A:CG33820 (85% identical), Drosophila melanogaster His2A:CG33823 (85% identical), Drosophila melanogaster His2A:CG33826 (85% identical), Drosophila melanogaster His2A:CG33829 (85% identical), Drosophila melanogaster His2A:CG33832 (85% identical), and 11 more. Paralogues in human: H2AC11 (99% identical), H2AC13 (99% identical), H2AC15 (99% identical), H2AC16 (99% identical), H2AC17 (99% identical), H2AC4 (99% identical), H2AC8 (99% identical), H2AC25 (98% identical), H2AC12 (98% identical), H2AC18 (98% identical), H2AC19 (98% identical), H2AC6 (98% identical), and 15 more.
Diseases named in the same sentence as H2AC7 in open-access papers:
H2AC7 is named in the same sentence as 3 diseases in open-access papers, as found by Europe PMC text mining. Sharing a sentence is not in itself a finding about the gene and the disease.
H2AC7 shares sentences with these, for which no sentence is quoted: cancer (1 paper); migraine (1); systemic lupus erythematosus (1).